FOXO1 (forkhead box O1)
Diseases named in the same sentence as FOXO1 in open-access papers (continued):
Sharing a sentence is not in itself a finding about the gene and the disease.
rhabdomyosarcoma (continued). "For example, in alveolar rhabdomyosarcoma (aRMS), the fusion oncogene PAX3::FOXO1 (or PAX7::FOXO1) binds SEs together with other MTFs, including MYOD, MYOG, and MYCN, to sustain proliferation, and their depletion leads to altered proliferation and cell death." (PMID 41444391, 2025). "Alveolar rhabdomyosarcoma (RMS), an aggressive pediatric soft tissue cancer, is driven by the oncogenic fusion transcription factor PAX3::FOXO1 (P3F) or PAX7::FOXO1." (PMID 41473312, 2025). "Accordingly, for rhabdomyosarcomas, a total of 20 specimens were tested by FISH and only two were found positive for the FOXO1 translocation (10%)." (PMID 40718211, 2025). "In alveolar rhabdomyosarcoma cells, the PAX3::FOXO1 fusion transcript has been demonstrated to suppress Hippo signalling through Ras associated domain family 4 (RASSF4) which modulates the activity of the MST1 kinase, leading to overexpression of YAP." (PMID 40983796, 2025). "In alveolar rhabdomyosarcoma (ARMS), a chromosomal translocation fusing FOXO1 to either PAX3 or PAX7 is present in about 80% of cases." (PMID 38473380, 2024). "In rhabdomyosarcoma, the fusion gene between PAX3 or PAX7 and FOXO1 is an important characteristic within the alveolar subtype." (PMID 37152023, 2023). "FOXO1, also known as Forkhead Homologue in Rhabdomyosarcoma (FKHR), was initially identified as a fusion protein with Pax3 in alveolar rhabdomyosarcoma." (PMID 35406686, 2022). "The PAX3-FOXO1 fusion protein contains the PAX3 DNA binding domains and the FOXO1 transactivation domain contributing to the majority of rhabdomyosarcoma cases via impairment of myogenic differentiation." (PMID 34595600, 2021). "Another round cell sarcoma, alveolar rhabdomyosarcoma (ARMS), exhibits skeletal muscle differentiation and is frequently driven by FOXO1 gene fusions." (PMID 33921435, 2021). "This is the case of chromosomal translocations fusing the genes PAX3 and FOXO1 in alveolar rhabdomyosarcoma, which result in the fusion of both RLs and the activation of transcription from PAX3 promoter by enhancers from the FOXO1 RL." (PMID 34295901, 2021). "Here we report that in fusion-positive rhabdomyosarcoma, a cancer of the muscle lineage, the chief oncogene PAX3-FOXO1 is driven by a translocated FOXO1 super enhancer (SE) restricted to a late stage of myogenesis." (PMID 32416589, 2020). "The human FOXO1 (also known as FKHR; forkhead in rhabdomyosarcoma) was first identified as the fusion partner of paired box protein (PAX) 3/7 in alveolar rhabdomyosarcoma, a paediatric tumour of skeletal muscle." (PMID 32372224, 2020). "In a majority of alveolar rhabdomyosarcomas (ARMS), PAX3 has been shown to undergo chromosome rearrangement with FOXO1/FKHR." (PMID 31614829, 2019). "Alveolar rhabdomyosarcoma, a muscle tumor in children, is typified by a translocation that fuses the PAX3 gene on chromosome 2 to the FOXO1 gene on chromosome 13." (PMID 25659124, 2015). "Biomarkers in use from these pathways include FOXO1 within the VEGF pathway, as a prognostic marker in rhabdomyosarcoma (as a fusion gene with PAX3) and also shown to be highly expressed in the infancy cluster of increased gene expression." (PMID 23941278, 2013). "No deletion or extra copy of FOXO1 locus was found in any of the 94 cases of alveolar rhabdomyosarcomas screened." (PMID 40666501, 2025). "95% of embryonic rhabdomyosarcomas are FOXO1 fusion-negative, which means that almost all embryonic rhabdomyosarcomas are FOXO1 fusion-negative rhabdomyosarcomas." (PMID 40161378, 2025). "While little is known about the molecular mechanisms of CIC::FOXO4 fusion oncoproteins, FOXO4 (also known as AFX) and FOXO1 (also known as FKHR) chimeras have been identified in MLL-rearranged acute leukemia (AFX::MLL) and alveolar rhabdomyosarcoma (PAX3::FOXO1)." (PMID 38882060, 2024).
rhabdomyosarcoma (continued). "With advancing genetic knowledge, FOXO1 rearrangements are increasingly recognised; these genes are found in 70-80% of alveolar rhabdomyosarcoma but not in embryonal rhabdomyosarcoma." (PMID 36843091, 2023). "In more recent studies, rhabdomyosarcoma is therefore classified as either FOXO1 fusion positive or fusion negative; patients with fusion positive tumours have a poorer prognosis." (PMID 36843091, 2023). "NGS results drastically changed the initial diagnosis, and thus the treatment modalities, in 3 cases (15%): the case with ETV6-NTRK3 fusion, the case with FUS-TFCP2 fusion, and the case of rhabdomyosarcoma (RMS) that was favored to be of the alveolar subtype and turned out to lack FOXO1 fusions." (PMID 34514574, 2021). "In alveolar rhabdomyosarcoma, for example, high expression of cytoplasmic and nuclear YAP1 has been documented, and the fusion oncogene paired box gene 3 (PAX3): forkhead box protein O1 (FOXO1) directly regulates increased expression of Ras‐association domain family 4 (RASS4)." (PMID 30979710, 2019). "Rhabdomyosarcoma is subclassified by the presence or absence of a recurrent chromosome translocation that fuses the FOXO1 and PAX3 or PAX7 genes." (PMID 31480361, 2019). "Similarly, rhabdomyosarcoma can result from fusion of PAX7 and FOXO1 genetic materials." (PMID 38540335, 2024). "For instance, the diagnosis of alveolar rhabdomyosarcoma (ARMS) is typically based on histopathological features, IHC results (most importantly desmin, MyoD1, and myogenin), and molecular results (RT-PCR for PAX3/PAX7–FOXO1 or FISH for PAX3/FOXO1 rearrangement)." (PMID 37621777, 2023). "Alveolar (fusion-positive) rhabdomyosarcoma (FP-RMS), an aggressive skeletal muscle cancer of childhood, often possesses chromosomal translocations, involving commonly PAX3 and FOXO1 genes, rarely PAX7-FOXO1, and in exceptional cases PAX3-INO80D and PAX3-NCOA1 fusions." (PMID 32416589, 2020). "An interesting site of FoxO1 expression is BAT, which can easily transdifferentiate into muscle and vice versa, while overexpression of a constitutively active Smoothened restricted to adipocytes has been shown to give rise to embryonic rhabdomyosarcomas (ERMS) with relative high penetrance." (PMID 28615069, 2017). "For stratification purposes, rhabdomyosarcoma is classified into fusion-positive RMS (alveolar rhabdomyosarcoma) and fusion-negative RMS (embryonal or spindle cell/sclerosing, FN-RMS) subtypes according to its PAX::FOXO1 fusion status." (PMID 40923514, 2025). "A final differential diagnosis could be with alveolar rhabdomyosarcoma, which can also display an alveolar pattern, but the diagnosis was ruled out by negativity of Myogenin and MyoD1 staining and no detection of PAX::FOXO1 fusion by NGS." (PMID 38643139, 2024). "Rhabdomyosarcoma (RMS) is the most common soft tissue sarcoma of childhood and is comprises 2 genetically defined subtypes: FOXO1 fusion positive (FP) and fusion negative (FN), which are characterized by activating mutations in receptor tyrosine kinase (RTK)/RAS pathways." (PMID 36282590, 2022). "Classically, alveolar rhabdomyosarcoma are differentiated into FOXO1-PAX positive vs. negative; however, embryonic rhabdomyosarcoma are sometimes included with fusion negative alveolar rhabdomyosarcoma, and there is some evidence that these subtypes are indistinguishable clinically." (PMID 31480361, 2019). "Similarly, in data from the NCBI, we found that the IFFO2 expression level in rhabdomyosarcoma patients with PAX3 and FOXO1 gene fusion, which is considered a predictor of adverse results in children with rhabdomyosarcoma, was lower than those in patients without PAX3 and FOXO1 gene fusion." (PMID 41359381, 2025).
breast carcinoma (194 papers, 2006 to 2026). "In breast cancer, decreased expression of FOXO1 has been linked to poor prognosis via interactions with the PI3K/Akt pathway, GATA3, and Annexin-1 expression." (PMID 39135158, 2024). "In breast cancer, the loss of FOXO1 activity is associated with resistance to endocrine therapy, while overexpression of FOXO1 has been shown to sensitize breast cancer cells to endocrine therapy." (PMID 38994962, 2024). "In our study, we fortunately strengthened the concepts that the FOXO1 served its suppressive role in metastasis of adipocytes-associated breast cancer through EMT pathways." (PMID 39135158, 2024). "In CRC, low expression of FOXO3 is associated with cancer progression in specimens with normal tissue, while high FOXO1 expression is associated with good prognosis in prostate and breast cancers." (PMID 37275916, 2023). "Correlation study of methylation and protein expression in samples having methylated FOXO1 promoter or FOXO1 expression loss with clinical parameters of Breast cancer patients from North Indian population." (PMID 35309123, 2022). "Our results also suggest the tumor suppressive role of FOXO1 in breast cancer and show a strong association of low protein expression with the histological grade (p = 0.05) and tumor size (p = 0.01) of breast cancer patients." (PMID 35309123, 2022). "For breast cancer, bladder cancer, and cervical cancer, FOXO1 deficiency indicates worse clinical outcomes through inducing cell cycle arrest and apoptosis." (PMID 35609322, 2022). "TRIB3 is positively associated with breast cancer stemness and progression by inhibiting FOXO1 degradation and increasing SOX2 transcription and the cellular stress-activated TRB3/USP9x-dependent Notch pathway in breast cancer." (PMID 36463181, 2022). "FOXO1 as a tumor suppressor has been associated with multiple types of malignancies, including colon, cervical, prostate, gastric and breast cancers." (PMID 33849069, 2021). "Dysregulation of FOXO1 is associated with multiple cancers such as prostate cancer, breast cancer and endometrial cancer." (PMID 33849069, 2021). "We have shown previously that in HER2+ breast cancer cells, loss of nuclear expression FOXO1 by constitutive activation of Akt at Ser473 contributes to trastuzumab resistance." (PMID 32708561, 2020). "Reduced expression of FoxO1 and FoxO3 is associated with resistance to conventional agents and with reduced efficacy of drug combinations in ovarian and breast cancer cells." (PMID 31906031, 2019). "Nuclear FOXO1 is associated with cisplatin and tamoxifen-resistance in gastric and breast cancer cells respectively." (PMID 25569080, 2015). "For example, the study of Guttilla and White indicate that the coordinately regulation of FOXO1 by miR-96 and miR-182 which involved in the miRNA-mRNA regulatory network was associated with the oncogenic state in breast cancer cells." (PMID 25874214, 2015). "Elevated gene expression of MDR1 (P-glycoprotein) is a major cause of chemoresistance in many cancer cells and FOXO1 has been shown to be a transcriptional activator of MDR1 in adriamycin-resistant breast cancer cells." (PMID 25569080, 2015). "Studies from our group, and others, have identified that the pathway directed along the Insulin-like Growth Factor (IGF) axis (specifically involving IGF-I, IGFBP3, down the PI3K/Akt cascade to FOXO1) is strongly associated with breast cancer outcomes." (PMID 24167614, 2013). "Immunoprecipitation studies confirmed that HuR associates with FOXO1 mRNA in MDA-MB-231 breast cancer cells and that HuR upregulates FOXO1 mRNA levels through increased mRNA stability." (PMID 23946796, 2013). "Here, we demonstrate that BITC treatment causes FoxO1-mediated autophagic death in cultured human breast cancer cells." (PMID 22457718, 2012). "We aimed to investigate the role of FOXO1 in obesity-associated-breast cancer." (PMID 39135158, 2024).
breast carcinoma (continued). "Obesity and the forkhead box O1(FOXO1) affect the survival of breast cancer patients, but the underlying mechanism remains unclear." (PMID 39135158, 2024). "However, further research is needed to evaluate FOXO1 significance in diagnostic and therapeutic targeting in breast cancer cases." (PMID 35309123, 2022). "Also, the FOXO1 promoter methylation exhibited significant association (p = 0.04) with the menopausal status of the female breast cancer patients, 65.38% (51/78) cases that showed promoter methylation were post-menopausal." (PMID 35309123, 2022). "However, the evaluation of FOXO1 promoter methylation and its expression at mRNA and protein level in different stages of breast cancer and its association with different clinical parameters is still not studied." (PMID 35309123, 2022). "This positive feedback loop causes FOXO1 nuclear accumulation and promotes breast cancer stemness." (PMID 31844113, 2019). "Similarly, a low ROS level in breast cancer stem cells is associated with an increased expression of Foxo1 and the glutathione biosynthesis genes Gss and Gclm32." (PMID 27091640, 2016). "In addition, studies from our group also reported that loss of FOXO1, a downstream protein within the Akt signaling pathway, is associated with reduced breast cancer outcome among underrepresented women." (PMID 24167614, 2013). "In addition up-regulation of miR-96 has been associated with the transformation or maintenance of breast cancer cells through the expression inhibition of the transcription factor FOXO1." (PMID 21829531, 2011). "References: René Aquarius, Comments on "KCTD12 promotes G1/S transition of breast cancer cell through activating the AKT/FOXO1 signaling," PubPeer, August 2024." (PMID 41944200, 2026). "BITC also triggers autophagic cell death in breast cancer cells, mediated by FoxO1, and this effect is prominent in multiple breast cancer cell lines." (PMID 40799801, 2025). "In this study, we identify Forkhead box O1 (FOXO1), a transcription factor essential for tumorigenesis and progression, as a key regulator of the UC in breast cancer cells." (PMID 40907897, 2025). "Functionally, we demonstrate that FOXO1 modulates the migratory ability of breast cancer cells through the regulation of ASL and arginine metabolism." (PMID 40907897, 2025). "These investigators also found that ABCA9 is under the control of FOXO1 (tumor suppressor), which is downregulated in breast cancer, due to the activation of the PI3K–AKT pathway, which phosphorylates FOXO1." (PMID 40427160, 2025). "It has been reported that aberrant SMAD3 and FOXO1 signaling is involved in trastuzumab resistance in breast cancer cells." (PMID 40925917, 2025). "In diverse cell lines, the basic levels of FOXO1 were lower in breast cancer cell lines and Hpa-V cells than normal breast cells." (PMID 39135158, 2024). "PAK1 is upregulated in various cancer types, integrates various signalling pathways, such as PI3K and RAS, and has been reported to phosphorylate and inactivate FOXO1 in breast cancer and FOXO6 in liver ageing." (PMID 39499086, 2024). "HuR interacts with FOXO1 mRNA and stabilizes its expression, thereby augmenting 5-fluorouracil (5-FU)-induced apoptosis in breast cancer cells." (PMID 38466341, 2024). "Conversely, QKI destabilizes FOXO1 mRNA and contributes to the oncogenesis and progression of breast carcinoma." (PMID 38466341, 2024). "After preliminary experiments, miR-135b showed evident relationship with FOXO1 in breast cancer development." (PMID 39135158, 2024). "Ambra1 (autophagy/Beclin 1 regulator 1) regulated the Akt/FoxO1/Bim pathway and conferred to cell apoptosis and chemosensitivity in breast cancer cells." (PMID 38773471, 2024). "We proposed that adipocytes promoted breast cancer invasion and migration through the FOXO1/miR-135b/ circCNIH4 axis." (PMID 39135158, 2024).
breast carcinoma (continued). "In consequence, our results suggested that FOXO1 act as one target of miR-135b and inhibit the invasion and metastasis of breast cancer." (PMID 39135158, 2024). "After coculturing with Hpa-V cells, the mRNA and protein levels of FOXO1 in breast cancer cell lines were suppressed." (PMID 39135158, 2024). "And we confirmed the tumor suppressive role of FOXO1 by analyzing its protein levels in paired breast cancer and normal tissues, and by examining the Kaplan-Meier survival curves of 1211 breast cancer patients from the TCGA dataset." (PMID 39135158, 2024). "Uev1A governed the Akt/FoxO1/Bim pathway and enhanced cell survival and chemoresistance in breast cancer cells." (PMID 38773471, 2024). "To identify the effect of FOXO1 on breast cancer cells, we constructed specific plasmid overexpressing FOXO1, then separately transfected the p-FOXO1 into the MDA-MB-231 and SkBr3 cells." (PMID 39135158, 2024). "To search for protein phosphatases that dephosphorylate FOXO1, we obtained data from a large proteomic analysis of breast cancer patients and calculated the Pearson correlation coefficients between FOXO1 and protein phosphatases." (PMID 38519029, 2024). "The results conveyed that the expression of FOXO1 was obviously lower in breast cancer tissues than normal breast tissues." (PMID 39135158, 2024). "In our study, adipocytes-induced reduction of FOXO1 mainly regulated the migration and invasion of breast cancer." (PMID 39135158, 2024). "In breast cancer tissues, the expression of circCNIH4 was positively related to FOXO1 expression by correlation curve." (PMID 39135158, 2024). "This provides possibilities of novel therapies by promoting FOXO1 and circCNIH4 expressions to counteract the adverse effects of adipocytes on breast cancer." (PMID 39135158, 2024). "In other words, the most remarkable regulations in breast cancer brought by FOXO1 was the changes in migration capability, along with the alterations in biomarker proteins of the epithelial-mesenchymal transition." (PMID 39135158, 2024). "When FOXO1 was depleted using an shRNA in the MCF7 human breast cancer cell line and HT29 human colon cancer cell line, cell growth was markedly inhibited." (PMID 38519029, 2024). "Decreased AQP3-19Y phosphorylation impaired SCAF11-mediated AQP3-5K K48-ubiquitination, resulting in compromised FOXO1 activity in breast cancer stem cell maintenance." (PMID 38136293, 2023). "GOLPH3 has the ability to promote tumorigenicity of breast cancer cells and it has an important relationship with the prognosis of breast cancer patients, perhaps by suppressing expression of FOXO1." (PMID 36967990, 2023). "Glioblastoma multiforme (GBM) and basal‐like breast cancer (BBC) harbor FOXO1‐driven embryonic stem gene expression signatures." (PMID 36602390, 2023). "The study has demonstrated the association of Cdc25A, a cell-cycle-activating phosphatase overexpressed in breast cancer, with poor prognosis, which enhances the stability of FOXO1, and thereby directly stimulates the transcription of MMP1." (PMID 38136293, 2023). "MiR-30 family has been reported to negatively regulate the AVEN expression in the breast cancer cell line, while Foxo1 has a positive regulatory effect on AVEN expression in regulatory T cells." (PMID 37908231, 2023). "The lower expression of FOXO1 implied an inferior OS for breast cancer patients, as well as a shortened recurrence-free survival (RFS) and distant metastasis-free survival (DMFS)." (PMID 38111678, 2023). "The AQP3/SCAF11/FOXO1 axis was identified as the mechanism by which CAP targets breast cancer stemness." (PMID 38136293, 2023). "Downregulation of FOXO1 in breast cancer is related to a worse prognosis in breast cancer, especially in HER2-positive subtypes." (PMID 37190065, 2023). "In a recent study, Zeng demonstrated that FOXO1, a gene significantly associated with PDCD1, downregulated copper homeostasis is a novel indicator of breast cancer prognosis and immune response." (PMID 37670938, 2023).